IL6 (interleukin 6)
Diseases named in the same sentence as IL6 in open-access papers (continued):
Sharing a sentence is not in itself a finding about the gene and the disease.
ovarian carcinoma (continued). "The lncRNA HOXA transcript at the distal tip (HOTTIP) enhances IL-6 expression by upregulating PD-L1 expression in neutrophils allowing ovarian cancer cells to escape the immune system." (PMID 36935487, 2023). "In ovarian cancer cells, the presence of IL-6 induces the expression of HIF-1α through the activation of STAT3." (PMID 37501379, 2023). "The discriminative ability of IL-6 for ovarian cancer in the pre-treatment serum of our patients has been validated in an independent cohort of advanced HGSOC." (PMID 36765633, 2023). "Patients with ovarian cancer and a higher value of Il-6 had shorter overall survival and shorter progression-free survival or even progression of disease after diagnosis." (PMID 37373969, 2023). "The area under the receiver operating curve and the sensitivity of serum TNF‐α in predicting ovarian cancer recurrence were higher than those of IL‐6 and IFN‐γ." (PMID 37904699, 2023). "Otherwise, Il-6 was observed as having a higher value in ovarian cancer, with a maximum of 79.75 ng/mL in a patient with serous ovarian cancer in IIIC, while it was 40.19 ng/mL in the case of a simple ovarian cyst." (PMID 37373969, 2023). "IL-6 is a pro-inflammatory cytokine produced by a number of cell types, including a variety of immune cells that affect target cells such as ovarian cancer cells via the JAK/STAT pathway." (PMID 37175439, 2023). "On the other hand, in our study, we observed a higher concentration of serum Il-6 in advanced stages of ovarian cancer and it was correlated with poor prognosis of the disease." (PMID 37373969, 2023). "The invasiveness of ovarian cancer cells is induced by various cytokines such as IL-10 and IL-6, which are secreted by the TAMs that have M2-like phenotypes and express CD206 and arginase-1 (ARG1)." (PMID 36757936, 2023). "In glioma or ovarian cancer models, Stat3 was phosphorylated both in cancer cells and macrophages by direct co-culture and promoted cancer cell proliferation and production of IL-6 or IL-10 from the macrophages." (PMID 37296952, 2023). "Two cutoff values, i.e., 400 pg/ml (92% sensitivity and 60% specificity) and 1,200 pg/ml (84% sensitivity and 87%), for IL-6 has been evaluated for stage I and stage II ovarian cancer subjects." (PMID 37746258, 2023). "Here, we report that IL-6 induces ovarian cancer cell migration only in the presence of glucose, and this effect is hampered by RV." (PMID 36675246, 2023). "Only Il-6 is statistically relevant to the histological serous type of ovarian cancer, which was revealed using Spearman correlation." (PMID 37373969, 2023). "Mean values of the markers CA125, HE4, CEA, CRP, PCT and Il-6 were higher in the group with a diagnosis of ovarian cancer." (PMID 37373969, 2023). "Previous studies have shown that the serum IL‐6 level in ovarian cancer patients is abnormally elevated." (PMID 37904699, 2023). "In mimicking in vitro this condition, we show that IL-6 promotes ovarian cancer cell migration only in the presence of glycolysis." (PMID 36675246, 2023). "Elevated IL-6 in ascites and in the serum of patients with advanced ovarian cancer has been most strongly correlated with poor survival, as it has in multiple other cancers." (PMID 36765633, 2023). "IL-6-dependent differentiation of CD4+ regulatory T cells has been stimulated by ovarian cancer ascites fluid in vitro." (PMID 36860657, 2023). "We demonstrated that IL-6 positively impinges on ovarian cancer cell proliferation and motility via epigenetic down-regulation of autophagy." (PMID 36675246, 2023). "The present work demonstrates, for the first time, that ovarian cancer cells migration relies on IL-6-induced aerobic glycolysis." (PMID 36675246, 2023). "Every patient who died because of the progression of ovarian cancer demonstrated a higher value of Il-6." (PMID 37373969, 2023).
ovarian carcinoma (continued). "As disease progression depends on various IL-6-related mechanisms in ovarian cancer, the IL-6 signaling pathway is an ideal target for drug development." (PMID 37047012, 2023). "Studies demonstrated that epithelial ovarian cancer growth and progression are promoted by the tumor necrosis factor a, interleukin 1β, and interleukin 6 produced by activated innate immune cells." (PMID 37445830, 2023). "The concentration of IL-6 was higher in the serum of patients with ovarian cancer compared to benign ovarian masses or normal ovaries (median IL-6: 28.3 vs. 6.4 vs. 1.2 pg/mL, p < 0.0001)." (PMID 36765633, 2023). "The aim of this study was to confirm the role of Il-6 compared to other markers in diagnosis and survival in ovarian cancer." (PMID 37373969, 2023). "HOTTIP promotes IL-6 secretion, thereby upregulating PD-L1 expression in neutrophils and ultimately promoting the ability of ovarian cancer cells to escape the immune system." (PMID 36935487, 2023). "The protumorigenic cytokine IL-6 is significantly elevated in ovarian cancer patients with confirmed thrombocytosis." (PMID 36831623, 2023). "Because of the activation of STAT3 by Il-6, it seems that the blockade of Il-6 and inhibition of this marker prolong survival of patients with ovarian cancer." (PMID 37373969, 2023). "Sensitivity and specificity of Il-6 in diagnosis of ovarian cancer were 46.8% and 77.8%, respectively, while for CA125, CRP and PCT were 76.6% and 63%; 68% and 57.5%; 36% and 77%, respectively." (PMID 37373969, 2023). "Evaluation of IL6 and CA-125 has also been reported to increase the prediction accuracy and determine better management for ovarian cancer." (PMID 37792745, 2023). "In our study, patients with progression of ovarian cancer were detected with higher levels of Il-6, CRP and PCT, which confirmed the inflammatory background of neoplastic disease." (PMID 37373969, 2023). "LncRNA HOXA transcript at the distal tip (HOTTIP) has been shown to promote immune escape in ovarian cancer by enhancing the binding between the transcription factor c-jun and interleukin-6 (IL-6) promoter." (PMID 37835376, 2023). "Additional studies have focused on the impact of LPA on the extracellular cytokine milieu, with LPA promoting the transcription of IL-6 and IL-8 in breast and ovarian cancer cells, while also diminishing type I interferon responses in ovarian cancer." (PMID 37655662, 2023). "A large number of cytokines have been reported as elevated in ovarian cancer ascites samples including IL-6, IL-8, IL-10, IL-15, IP-10/CXCL10, MCP-1/CCL2, Mip1α/CCL3, Mip1β/CCL4, MDC, and VEGF." (PMID 36860657, 2023). "In our study, we confirmed a statistically significant association between the diagnosis of ovarian cancer and levels of CA125, HE4, CRP, PCT and Il-6." (PMID 37373969, 2023). "Statistically significant associations of overall survival were observed with levels of CA125, HE4, CRP, PCT and Il-6 measured at the time of diagnosis of ovarian cancer." (PMID 37373969, 2023). "IL-6 accumulates in the serum and ascitic liquid of ovarian cancer patients, correlating with metastasis and poor clinical outcome." (PMID 36675246, 2023). "Specifically, IL-6, and IL-8, are the most abundant and play important roles in ovarian cancer cell survival, proliferation, adhesion, migration, and invasion." (PMID 35574025, 2022). "The expression levels of norepinephrine and IL-6 in ovarian cancer tissues of stressed patients were significantly increased compared to those in non-stressed patients (matched for age and disease stage)." (PMID 35338118, 2022). "Much higher serous IL-6 concentrations have been reported from patients with ovarian cancer (up to 41.23 pg/mL;) or acute appendicitis (up to above 1000 pg/mL;)." (PMID 35735559, 2022). "In ovarian cancer, Cytokines IL-6 and IL-8 are activated by NF-κB andpromote tumor growthvia immunosuppression." (PMID 36531159, 2022).
ovarian carcinoma (continued). "In this study, the authors found a significant IL-6 overexpression in the stromal fibroblasts of ovarian cancer samples from patients that had been treated with cisplatin." (PMID 36361682, 2022). "Expression of TNFR2 on Tregs is elevated in ovarian cancer patients, possibly due to increased interleukin 6 (IL-6) levels found in the cancer microenvironment." (PMID 36428581, 2022). "For example, interleukin-6 (IL-6) released from ovarian cancer cells can stimulate the secretion of thrombopoietin in the liver and it eventually leads to thrombocytosis." (PMID 36158646, 2022). "IL6 cytokine expression has been shown to be inversely correlated with AET response in ovarian cancer cell lines." (PMID 36230597, 2022). "IL-6 can also induce HIF-1α activity via JAK/STAT signaling, which has been shown to be associated with chemoresistance to cisplatin in ovarian cancer." (PMID 36230617, 2022). "We show that IL-6 inhibits autophagy in ovarian cancer cells via miRNAs downregulation of ARH-I, an effect contrasted by the nutraceutical resveratrol (RV)." (PMID 35565270, 2022). "The overactivation of IL-6 pathways, particularly activation of STAT3, has been implicated in the aggressiveness of ovarian cancer." (PMID 36429126, 2022). "It was found through multivariate logistic regression analysis that decreased ADPN level and increased D-D, hsCRP, IL-6, CA125, and HE4 levels were independent risk factors affecting the development of ovarian cancer." (PMID 35431651, 2022). "While there is a lack of information that relates IL-1α to paclitaxel, previous works have described that paclitaxel induces the upregulation of IL-6 in ovarian cancer cells through the TLR4–NF-κB cascade." (PMID 35163066, 2022). "In conclusion, the findings reported herein demonstrate a link between IL6/LIF cytokine signaling in the ovarian cancer tumor microenvironment and tumor cell estrogen signaling." (PMID 36230597, 2022). "IL-6 is also accompanied by chemotherapy resistance, further proving the role of this cytokine in ovarian cancer outcomes." (PMID 34751020, 2022). "In vitro studies have shown that norepinephrine promotes the release of the pro-inflammatory cytokines IL-6 and IL-8 from ovarian cancer cells by acting on the β2-adrenergic receptor signaling pathway." (PMID 35338118, 2022). "Here, we provide evidence that the chronic administration of RV induces a cell quiescent state with features of cell dormancy in ovarian cancer cells and, more interestingly, that this dormant state persists also when the cells are challenged with IL-6." (PMID 35565270, 2022). "CCL2 from mesenchymal stromal cells act on ovarian cancer cells and induces IL-6 secretion for chemoresistance dependent on IL-6 and PYK2." (PMID 36403055, 2022). "Treatment of SKOV3 and IGROV-1 ovarian cancer cells with IL-6 led to a E-cadherin to N-cadherin switch and the upregulation of mesenchymal markers Snail and Twist." (PMID 35565396, 2022). "IL-6 is prevalent in the TME of ovarian cancer and, via complex signalling and response by both cancer and stromal cells, is able to promote proliferation, angiogenesis, and migration while inhibiting apoptosis." (PMID 36429126, 2022). "It has been indicated that pro-inflammatory cytokine IL-6 is elevated in the serum of patients with ovarian cancer and it is related to poor outcomes." (PMID 34751020, 2022). "It stimulates the production of TNF-α and interleukins IL-6 and IL-12 in adipocytes as well as in immune system cells involved in the pathogenesis of ovarian cancer." (PMID 35453670, 2022). "We conducted clustering analysis of the TCGA ovarian cancer dataset based on GSVA enrichment scores of IL6, JAK-STAT, and tumor angiogenesis pathways and identified 10 clusters with distinct expression patterns." (PMID 35313341, 2022). "In vivo, neutralizing antibodies to both IL-8 and IL-6 prevented homing to adipose microenvironment in the SKOV3ip1 ovarian cancer xenograft model." (PMID 35565396, 2022).
ovarian carcinoma (continued). "Here, we investigated the mechanisms involved in the reciprocal regulation of autophagy and cell dormancy in ovarian cancer cells challenged with IL-6 to mimic the pro-inflammatory tumor microenvironment." (PMID 35565270, 2022). "In patients with platinum-resistant ovarian cancer, however, targeting a specific cytokine/chemokine (e.g., monoclonal antibodies against IL-6 or TNF-α) has only shown a transient and limited antitumor effect." (PMID 36386196, 2022). "Mechanistically, IL-6 and RV oppositely regulate autophagy-dependent ovarian cancer cell proliferation and dormancy through the modulation of miR-1305, which is proven to bona fide target ARH-I." (PMID 35565270, 2022). "The results of the univariate analysis showed that abnormal ADPN, D-D, hs-CRP, IL-6, CA125, and HE4 levels were related to risk factors affecting the development of ovarian cancer." (PMID 35431651, 2022). "The pro-inflammatory environment in ascites fluid induces TAMs to their tumor promoting phenotype, specifically through the pro-inflammatory cytokines IL-6 and IL-10 as well as mucins, such as cancer antigen (CA) 125, released by ovarian cancer cells." (PMID 35574025, 2022). "IL-6 is involved in many tumor types and has been found to be highly expressed in patients with ovarian cancer." (PMID 36230617, 2022). "It was shown in vitro that the levels of TNF-α and IL-6 mRNA were 1000-fold higher in ovarian cancer cells than in normal ovarian epithelial cells." (PMID 35453670, 2022). "IL-6/STAT3 activation in the TAMs also enhances the expression of Rab family proteins to facilitate CDDP resistance in ovarian cancer." (PMID 36359776, 2022). "Ovarian cancer patients have been found to have a higher concentration of inflammatory cytokines such as IL-6, CCL2/MCP-1, and TNF-α, which play an important role in the disease’s genesis and progression." (PMID 36386196, 2022). "Numerous cytokines involved in cell-mediated immunity, including IFN-γ, IL-6, MHC, and TNF-α molecules, have been associated with increased growth and patient prognosis in ovarian cancer." (PMID 36386196, 2022). "Prior work has demonstrated that LIF and IL6 cytokines in ovarian cancer ascites promote the differentiation of monocytes into immunosuppressive tumor-associated macrophages." (PMID 36230597, 2022). "It was revealed through univariate analysis that abnormal ADPN, D-D, hs-CRP, IL-6, CA125, and HE4 levels were related risk factors affecting the incidence of ovarian cancer." (PMID 35431651, 2022). "IL-6 expression in ovarian cancer patient tumours and serum both increase with disease stage, whilst high tumour IL-6 levels inversely correlate with patient survival." (PMID 35020853, 2022). "Cells were chronically treated with interleukin-6 (IL-6) to mimic in vitro the pro-inflammatory TME found in ovarian cancer patients." (PMID 35565270, 2022). "Inhibition of NF-κB leads to decreased levels of IL-6 and IL-8 in ovarian cancer cells indicating the direct correlation between NF-κB and ovarian cancer progression." (PMID 36531159, 2022). "IL-6 disrupts autophagy in ovarian cancer cells via miRNAs downregulation of ARH-I, an effect contrasted by the nutraceutical protein restriction mimetic resveratrol (RV)." (PMID 35565270, 2022). "IL-6 was also found to increase the activation of Tregs and to enhance the migratory and invasive abilities of ovarian cancer cells through the JAK-STAT3 signaling pathway, involved in cancer progression, and increased EMT." (PMID 35574025, 2022). "We previously showed that IL-6 is increased in ovarian stromal cells and enhances the aggressive behavior of ovarian cancer." (PMID 36430324, 2022). "In ovarian cancer patients, both mAbs have shown good tolerability profiles and effective IL-6/IL-6R blockade, characterised by decreased serum C-reactive protein (CRP) and STAT3 activation and increased serum IL-6 and soluble IL-6R." (PMID 35020853, 2022).
ovarian carcinoma (continued). "Cancer-associated fibroblasts (CAFs)-derived inflammatory cytokines such as IL-6 and IL-8 have been shown to promote ovarian cancer cell proliferation and motility through the downregulation of autophagy in the migrating cells." (PMID 35565270, 2022). "The applicability of both biosensors was verified in clinical investigations of ovarian cancer and endometrial cyst resection by the measurement of IL-6 levels in the plasma of patients, showing agreement of the results obtained with both biosensors." (PMID 35735559, 2022). "Namely, senescent PMCs were able to induce the pro-angiogenic phenotype in ovarian cancer cells in IL-6/TGF-β1-dependent mechanism." (PMID 35883110, 2022). "C-reactive protein (CRP), interleukin-6 (IL-6), and tumor necrosis factor-alpha (TNF-α) serum markers have shown to be higher in women with malignant ovarian tumors while there is uncertainty if serum levels are associated with unique GI microbes." (PMID 35740687, 2022). "Then, following our inclusion criteria, the final 55 articles involving IL6 assessed in serum and ascitic fluid of ovarian cancer patients were added for the meta-analysis." (PMID 34945807, 2021). "Additional studies with a larger sample of patients are needed to confirm the role of IL-6 in ovarian cancer diagnostics as well as further evaluate the clinical importance of IL-8 and TNF-α in patients with ovarian carcinoma and benign cystic lesions." (PMID 34573967, 2021). "Simultaneously, acacetin reduced mesothelial cell-induced transcripts and production of pro-inflammatory cytokine IL-6 and IL-8 in ovarian cancer cells." (PMID 34886812, 2021). "In ovarian cancer, tumor-driven unremitting expression of Satb1 was reported to enhance Galectin-1 and interleukin 6 (IL-6) production in activated inflammatory DCs, resulting in immune suppression and contributing to malignant progression." (PMID 34884995, 2021). "TAMs induce the invasive potential of ovarian cancer cells by secreting IL-6 and TGF-β, along with the production of MMPs." (PMID 34912809, 2021). "In contrast to the concentrations of adiponectin, those of IL-6 are reported in the literature for ascites in ovarian cancer." (PMID 34572929, 2021). "Multiple pro‐tumourigenic functions have been assigned to IL‐6 in ovarian cancer including invasion, migration, EMT, proliferation, overexpression of metalloproteases and chemoresistance." (PMID 34841720, 2021). "A correlation between IL-6 levels in blood and ascites in the course of cancer, including ovarian cancer, has been observed in various studies." (PMID 34572929, 2021). "It should be noted that past studies have also reported elevated levels of IL-6 in ovarian cancer patients." (PMID 34573967, 2021). "In fibroblasts senesced upon exposure to PCT, the activation of STAT3 was linked with hypersecretion of IL-6, i.e., one of the agents whose mRNA and protein were upregulated in DIPS ovarian cancer cells." (PMID 34674640, 2021). "In vitro treatment of CAFs from primary human ovarian cancer with cisplatin enhanced their chemoprotective properties in an IL-6-dependent manner." (PMID 34201616, 2021). "Using an in vitro model of ovarian cancer, it has been demonstrated that IL-6 produced by TAM attributes to the elevation of liver-derived acute-phase proteins." (PMID 33550983, 2021). "A previous section explains that NE can induce the production of IL-6 and IL-8 in ovarian cancer cells and promote angiogenesis and metastasis." (PMID 34307378, 2021). "Taking into account the current state of knowledge, further studies can be strongly recommended in order to transfer the results of the existing studies on IL-6 in ovarian cancer to clinical use." (PMID 34572929, 2021). "One study showed that in pre-operative ovarian cancer patients, serum IL-6 levels were higher compared to controls or patients with a benign tumor." (PMID 34503128, 2021).